LINC00842 (long independently transcribed non-coding RNA 842)
Gene: Long non-coding RNA gene on chromosome 10 (46,398,362 to 46,487,793, forward strand). Ensembl gene ENSG00000285294.
Diseases named in the same sentence as LINC00842 in open-access papers:
LINC00842 is named in the same sentence as 3 diseases in open-access papers, as found by Europe PMC text mining. Sharing a sentence is not in itself a finding about the gene and the disease. The quoted sentences say what the papers report.
cancer (1 paper, 2021). A tumor composed of atypical neoplastic, often pleomorphic cells that invade other tissues. "Overexpressed LINC00842 may directly interact with acetylated PGC-1α, an important transcription co-regulator in the metabolic pathways, and blocks SIRT1 to deacetylate acetylated PGC-1α, resulting in metabolic remodeling, i.e., enhancing anabolism but reducing catabolism in cancer cells." (PMID 34158490, 2021).
tumor (1 paper, 2026). "LINC00842 is associated with calcium ion binding, potentially leading to metabolic remodeling and alterations in the tumor microenvironment." (PMID 40988561, 2026).
LINC00842 also shares sentences with these, for which no sentence is quoted: pancreatic cancer (1 paper).